CCNB2 (cyclin B2)
Diseases named in the same sentence as CCNB2 in open-access papers (continued):
Sharing a sentence is not in itself a finding about the gene and the disease.
adenocarcinoma (3 papers, 2012 to 2022). A common cancer characterized by the presence of malignant glandular cells. "They constitute an interesting study where they discovered the expression of three genes (CDK1, CCNB2 and CDC25A) that may predict a poor prognosis in an adenocarcinoma patient." (PMID 35884982, 2022).
infection (2 papers, 2008 to 2024). The state of being infected such as from the introduction of a foreign agent such as serum, vaccine, antigenic substance or organism. "Interestingly, the results of the Q-ChIP experiments performed after infection with the DN-NF-YA expression vector indicate that the heterochromatin protein HP1α does not bind these promoters although a week recruitment is observed on cyclin B2 promoter." (PMID 18431504, 2008). "NN1172-infection leads to the down-regulation of many genes related to cell cycle and DNA replication genes, including MCM 2 ~ 6, CDK1 ~ 2, CCNB2, ANAPC2, MAD2L1, WEE1, RBL1, RB1." (PMID 38362295, 2024). "Furthermore, seven genes (CDK1, TYMS, MCM5, KIF11, CCNB2, MAD2L1, and MCM4) have been identified as core hub genes involved in cell-cycle regulation, potentially serving as mediators in the pathogenesis triggered by NN1172 infection within the thymus." (PMID 38362295, 2024).
CCNB2 also shares sentences with these, for which no sentence is quoted: colorectal adenocarcinoma (6 papers); pituitary adenoma (6); esophageal cancer (3); melanoma (3); invasive ductal carcinoma (2); Lung Squamous Cell Carcinoma (2); multiple myeloma (2); uterine corpus endometrial carcinoma (2); viral infection (2); adrenocortical tumors (1); astrocytoma (1); benign prostatic hyperplasia (1); brain glioma (1); Burkitt lymphoma (1); chronic lymphocytic leukemia (1); dengue fever (1); Dengue hemorrhagic fever (1); diabetic nephropathy (1); endometrioid endometrial carcinomas (1); endotoxemia (1); Ewing sarcoma (1); Hyperinsulinemia (1); Infertility (1); large cell lung cancer (1); laryngeal carcinoma (1); malaria (1); medulloblastoma (1); mesothelioma (1); neuroblastoma (1); oral cancer (1).
A further 10 diseases each share a sentence with CCNB2 in 1 paper.